HIF1A (hypoxia inducible factor 1 subunit alpha)
Diseases named in the same sentence as HIF1A in open-access papers (continued):
Sharing a sentence is not in itself a finding about the gene and the disease.
tumor (continued). "Moreover, tumor-associated macrophages promote aerobic glycolysis and resistance to apoptosis of BC cells through extracellular vesicle transmission of HIF-1α stabilizing long noncoding RNA (HISLA), while its blockage inhibits glycolysis and chemoresistance of BC in vivo." (PMID 32806533, 2020). "Moreover, HIF-1α is linked to the expression of immunosuppressive molecules in tumor cells, which could potentiate EMT induction through TGF-β signaling." (PMID 32322559, 2020). "Moreover, the patients with high FDG-uptake were significantly associated with the progression of tumour size, T factor, lymphatic invasion, venous invasion, stage, the high expression of HIF1-A and GLUT1 and the low expression of CD8, PD-L1 and E-cadherin compared to those with low FDG-uptake." (PMID 32238919, 2020). "Consequently, mRNAs encoding VEGF-A, -C, -D, FGF-2, HIF1A or DLL4 that are expressed by tumour cells or microenvironment (such as DLL4 expressed by TIP cells which are furthest away from the circulating blood are still efficiently translated while cap-dependent initiation is compromised." (PMID 32111004, 2020). "Thus, FGF23 production and local inflammation may be interdependent in the microenvironment of the tumor depending on hypoxia, HIF-1α activation, and tumor-associated macrophages." (PMID 33520985, 2020). "Moreover, it is known that HIF1α represses DNA repair genes, which could account for an increased mutation burden and tumor immunogenicity." (PMID 32231135, 2020). "The catabolic phenotypes observed in cancer-associated fibroblasts (CAFs) are driven by multiple cell signaling pathways including loss of caveolin-1 and the activation of HIF-1α and NF-κB signaling, which may serve as metabolic vulnerabilities in the metabolic rewiring of the tumor-CAF network." (PMID 32766253, 2020). "Likewise, this molecule could be a novel diagnostic and prognostic indicator for NB and other tumours regulated by HIF1α." (PMID 31511046, 2019). "Due to its effect on vascular tissue around a tumor, radiation causes vascular tissue damage followed by an oxygen diffusion disorder between the tissue and vessels and, subsequently, tissue hypoxia, which trigger increased expression of hypoxia-inducible factor (HIF)-1α." (PMID 30732625, 2019). "Interestingly, miR-210 can negatively regulate HIF-1α expression by directly targeting its mRNA forming a negative-feedback loop, and disruption of this loop has been implicated in autoimmune diseases and tumor initiation." (PMID 31717786, 2019). "NTHi-driven tumor promotion is associated with significant up-regulation of HIF-1α, and HIF-1 target genes, suggesting that HIF-1 activation during COPD-like inflammation that is independent of tobacco smoke may provide a crucial link between COPD and lung cancer." (PMID 30250643, 2018). "However, we cannot exclude additional alterations in the microenvironment upon sudden removal of HIF-1α-deficient NK cells, particularly changes in the cytokine milieu and the functionality of other immune cell subsets, that may promote tumour growth." (PMID 29150606, 2017). "Moreover, the reduced cytotoxic potential in HIF-1α-deficient NK cells could impair the interception and elimination of intravasated tumour cells in the circulation, and hence facilitate pulmonary metastasis by an additional mechanism." (PMID 29150606, 2017). "In consequence HIF-1α driven survival factors are expressed in hypoxic areas from tumor cells, cancer associated fibroblasts and immune cells and thereby may protect certain subpopulations of tumor cells from apoptosis or necrosis." (PMID 28402937, 2017).
tumor (continued). "In addition, we implied that RBMS3 might modulate the location of HIF1A and associate with tumor angiogenesis." (PMID 27902480, 2017). "Hence, we determined whether VEGF-dependent signalling to the tumour endothelium was affected by the loss of HIF-1α in NK cells." (PMID 29150606, 2017). "As PGCC cells are endowed with reduced proliferative rate in vitro combined with accelerated tumor growth capacity, the induction of HIF1α protein levels in the CSL-deficient cells may underlie their enhanced growth rates, invasive capacity, and accelerated tumor growth." (PMID 27066863, 2016). "The cells in the tumor stroma, including tumor infiltrating lymphocytes (TILs), tumor associated macrophages (TAMs) and cancer associated fibroblasts (CAFs) have been demonstrated to play different roles in tumor development and progression under the influence of hypoxia and HIF-1α." (PMID 27634881, 2016). "We performed xenograft injections of R132H IDH1 cells expressing either WT or V737N β1 integrin to test whether enhancing cellular mechanosignalling in mutant GBMs would increase tumour aggression and, if so, whether this increase would be associated with elevated HIF1α and TNC expression." (PMID 27820599, 2016). "Thus, HIF1α-dependent transcription of survivin may mediate cell survival under the low oxygen conditions commonly associated with tumor growth." (PMID 26584646, 2015). "In addition to this hypoxia-dependent stabilization system, a range of other genetic alterations, such as activation of oncogenes, loss of function of tumor suppressor genes, and mutations in metabolic enzyme genes can also activate HIF-1α and thereafter promote the Warburg effect." (PMID 24810689, 2014). "HIF-1α which causes glycolytic environment, such conditions may tip the balance into a state when IL-12 production is replaced by IL-23, that is, a shift from anti-tumor to pro-tumor." (PMID 24782866, 2014). "Thus, increased HIF-1α activity resulting from loss of tumor suppressor gene function may also contribute to the overexpression of VEGF, which is observed in a wide variety of human cancers." (PMID 25548899, 2014). "Thus, our data suggest that Rb plays an essential role in regulating the amplitude of the hypoxic response for genes regulating both angiogenesis and metastasis and that loss of Rb leads to exacerbated expression of HIF1α target genes that regulate tumor progression." (PMID 24919196, 2014). "Because increased expression of HIF-1α and CA IX in various tumors is believed to be associated with poor prognosis of cancer patients, an understanding of their involvement in the induction of tumor cell proliferation and consequent tumor growth has clinical relevance." (PMID 24886661, 2014). "Although the precise molecular mechanism of regulated CAIX shedding remains to be clarified, previous studies showed that dysregulation of HIF-1α could be caused by mutation in the von Hippel-Lindau (VHL) tumour suppressor gene or activation of the epidermal growth factor receptor (EGFR)." (PMID 20461082, 2010). "However, HIF-1α knockdown in hypoxic tumor cells caused the increase of miR-20b." (PMID 19893619, 2009). "Indeed, a positive association between tumour grade and HIF-1α has been reported." (PMID 15328513, 2004). "HIF1α signaling is essential for cancer cells to adapt to hypoxia (low oxygen levels) and for tumor growth, metastasis, and glycolysis reprogramming." (PMID 41459628, 2026). "Hypoxia within the tumor microenvironment induces hypoxia-inducible factor-1α (HIF-1α), which promotes aberrant angiogenesis by upregulating vascular endothelial growth factor (VEGF) and, subsequently, delta-like ligand 4 (DLL4) in endothelial cells." (PMID 41683994, 2026). "The elevated expression of HIF-1α has been proved to promote cellular processes and facilitate tumor progression." (PMID 41535418, 2026).
tumor (continued). "Beyond its metabolic role, lactate also acts as a signaling molecule by entering vascular endothelial cells via MCT1, where it stabilizes HIF-1α and activates pro-angiogenic pathways such as NF-κB/IL-8, thereby promoting tumor angiogenesis." (PMID 41491598, 2026). "Lactate activates PKA/cAMP pathways and promotes immunosuppressive tumor-associated macrophages (TAMs), whereas succinate signals through succinate receptor 1 (SUCNR1) to reinforce HIF-1α-dependent transcription and M2-like programming." (PMID 41828519, 2026). "Among 16 natural compounds evaluated, isoxanthohumol (IXN), a prenylated flavanone, emerged as the most potent, suppressing both hypoxia-induced HIF-1α accumulation in tumor cells and VEGF-induced DLL4 expression in endothelial cells." (PMID 41683994, 2026). "Elevated HIF‐1α expression is consistently observed across diverse tumor types, with HCC representing a prominent example of this dysregulation." (PMID 41541658, 2026). "Clinical studies have shown an inverse correlation between vitamin C levels in tumor tissues and HIF-1α activity." (PMID 41403402, 2026). "Tumor HIF-1α expression was significantly higher in patients with pathological stage III disease compared with stage I-II disease (40% vs. 15%, p = 0.023)." (PMID 42193129, 2026). "HIF-1α promotes dormancy under hypoxia and facilitates tumor angiogenesis to increase supply of oxygen." (PMID 41438587, 2026). "It is previously reported that fatty acids (FAs) released from cancer‐associated adipose tissue enhance hypoxia‐inducible factor‐1α (HIF‐1α) expression in cancer cells, promoting tumor progression." (PMID 41160815, 2026). "In regular conditions, the HIF‐1α protein undergoes hydroxylation through prolyl hydroxylases, which leads to its destruction using the von Hippel–Lindau tumor suppressor mechanism." (PMID 41521160, 2026). "In summary, the regulatory effects of anti-tumor drugs on HIF-1α can affect tumor dormancy and awakening during therapy, and individual differences of HIF-1α need to be considered when chemotherapy drugs were selected." (PMID 41438587, 2026). "This relationship forms a HIF-1α/NF-κB P65-mediated positive feedback loop that boosts the proliferative and tumor-enhancing capacities of GSC and immunosuppressive microglia." (PMID 42138075, 2026). "Organoid models exposed to tumor-promoting factors demonstrated enhanced KRASG12C/HIF-1α/β co-expression, further supporting their functional interplay." (PMID 41531732, 2026). "On one hand, moderate levels of ROS can promote tumor cell proliferation and survival by activating signaling pathways such as hypoxia-inducible factor 1-alpha (HIF-1α) and transcription factor NF-κB." (PMID 41567244, 2026). "It influences the phosphorylation and degradation of HIF1α, improving the stemness, chemoresistance, and metastatic potential of tumor stem cells." (PMID 41614928, 2026). "Treatment efficacy can improve when engineered nanoparticles are focused on HIF‐1α because such nanoparticles can specifically block hypoxic tumor cells." (PMID 41521160, 2026). "Recent studies have shown that hypoxic tumor microenvironments markedly reduce cisplatin sensitivity through HIF-1α – dependent signaling and disrupted redox homeostasis." (PMID 41526224, 2026). "It elucidates HIF-1α's role in directly promoting tumor cell proliferation, invasion, and drug resistance, while also remodeling the tumor microenvironment to regulate immune responses." (PMID 41988193, 2026). "These subtypes regulate tumor cell proliferation, invasion, apoptosis, and autophagy balance, respectively, and promote malignant progression by activating the HIF-1α pathway through regulation of the P300/CBP protein complex." (PMID 41614928, 2026). "Laboratory studies have demonstrated that lipid nanoparticles containing HIF‐1α siRNA resulted in major tumor reduction." (PMID 41521160, 2026).
tumor (continued). "Significantly, these techniques operate independently of varying HIF‐1α expression across various tumor types, providing a more broadly applicable methodology." (PMID 41521160, 2026). "The imbalance between oxygen supply and consumption in the tumor microenvironment induces hypoxia, which activates hypoxia-inducible factor-1α (HIF-1α) signaling." (PMID 41710663, 2026). "Rescue experiments confirm that the tumor‐suppressive effects of circIST1 silencing are reversed upon inhibition of these miRNAs or overexpression of HIF‐1α." (PMID 41541658, 2026). "Acriflavine‐mediated HIF‐1α inhibition significantly suppressed tumour proliferation and concurrently increased apoptosis in both PDX tumours, as evidenced by Ki‐67 and cleaved caspase‐3 staining." (PMID 41482854, 2026). "VEGFA differed significantly between controls and both tumor grades G2 and G3, and we observed a positive correlation for HIF1A and VEGFA with EC grading." (PMID 39888575, 2026). "HIF1A-AS2 then directly binds to the Gli1 protein to cooperatively regulate the expression of HIF-1α itself, hastening the growth of the tumor." (PMID 41614928, 2026). "In HCC, HIF‐1α functions as a central mediator within hypoxic niches, where it initiates tumor autophagy and augments cancer stemness properties." (PMID 41541658, 2026). "In normoxic cells, HIF-1α is quickly degraded whereas in the hypoxic niche of an HCC tumour, it is stabilized, dimerizes with HIF-1β and translocates to the nucleus at a slow rate." (PMID 41476776, 2026). "In its subnetwork, leptin is linked to HIF‐1α, IL‐1β, and IL‐6, suggesting some influence over the control of those drivers' downstream effects such as EMT and tumor invasion." (PMID 41450167, 2026). "The isoform-specific dysregulation of HIFs underscores divergent hypoxic pathway activation under mutant KRAS conditions, with elevated HIF-1α/β promoting tumor invasion and metastasis in PNETs." (PMID 41531732, 2026). "STAT3 and HIF-1α cooperate to regulate gene expression under hypoxic conditions, enhancing tumor survival, angiogenesis, and metabolic adaptation." (PMID 41596231, 2026). "QRT‐PCR analysis of 30 paired HCC clinical samples revealed that HIF‐1α was significantly upregulated in tumor tissues compared to adjacent non‐tumor tissues." (PMID 41541658, 2026). "This study investigated the anti-tumor mechanism of Rhaponticin (Rha), focusing on the metabolic/epigenetic axis involving hypoxia-inducible factor 1α (HIF-1α), glycolysis, and histone H3K18 lactylation (H3K18la)." (PMID 42316296, 2026). "Collectively, these findings demonstrated that hypoxia enhances KL-6 expression in BC cells, partly mediated by HIF-1α, and that KL-6 contributes to tumor cell invasion." (PMID 41416421, 2026). "Further, PD-L1 is considered to be a direct target of hypoxia-induced factor-1α (HIF-1α), which can also increase glycolysis in tumor cells by regulating the expression of glucose transporter 1 (GLUT-1)." (PMID 40668270, 2026). "Hypoxia-inducible factor-1alpha (HIF-1α) plays a critical role in tumor progression and remodeling of the tumor immune microenvironment." (PMID 41975646, 2026). "Illustrating impact in hypoxic cells, in tumor cells, and normoxic cells leading to the destruction of HIF‐1α." (PMID 41521160, 2026). "The master regulation molecule HIF‐1α controls cell adjustment to hypoxic situations and guides tumor development together with blood vessel growth and forces tumors to become resistant to therapy." (PMID 41521160, 2026). "This increase positions CCL2 as a key player in obese condition among the target cytokines influenced by HIF‐1α, highlighting its crucial role in the tumor microenvironment." (PMID 41160815, 2026). "HOTAIR can regulate HIF-1α expression in renal cell carcinoma by sequestering the tumor suppressor miR-127." (PMID 41614928, 2026).
tumor (continued). "We analyzed the mRNA expression levels of major proangiogenic molecules on the tumor surface and tumor depth, namely HIF1α, HIF2α, HIF3α, VEGF-A, VEGFR1, VEGFR2, and ETS-1." (PMID 41359448, 2026). "Functional studies in GBM cell lines, patient-derived cultures, and tumor models demonstrate that TRIM25-mediated HIF-1α stabilization promotes tumor proliferation, invasion, and angiogenic potential." (PMID 42020378, 2026). "HIF‐1α overexpression creates aggressive tumor phenotypes so researchers consider it a vital therapeutic target in cancer management." (PMID 41521160, 2026). "It is a crucial stage in the development of invasive carcinoma from carcinoma in situ, and there is a significant correlation between the density of tumor microvessels and the expression level of HIF-1α." (PMID 41614928, 2026). "CcRCC is characterized by increased expression of genes that promote fatty acid synthesis and glycolysis due to HIF1α and HIF2α activation resulting from the near universal loss of the VHL tumor suppressor gene." (PMID 39874221, 2025). "HIF-1α occupies a central role in cancer biology, exerting profound effects on tumor progression and the IVM." (PMID 39981236, 2025). "We further examined the impact of HIF-1α on subcutaneous tumor formation in GBM through in vivo experiments." (PMID 39781344, 2025). "It activates over 100 genes involved in abnormal proliferation, metabolic reprogramming, invasion, metastasis, and therapy resistance, with elevated HIF-1α expression strongly correlated with tumor initiation, progression, and poor prognosis." (PMID 41256331, 2025). "Nevertheless, the specific function of HIF-1α in controlling autophagy can differ based on the cellular circumstances and environmental signals found in the tumor microenvironment." (PMID 40004215, 2025). "Prior studies have shown that the expression of HIF-1α is closely related to the oxygenation state of the tumor." (PMID 40444079, 2025). "The hypoxia-inducible factor-1 alpha (HIF1α) is one of the major drivers of angiogenesis in tumor cells." (PMID 39953610, 2025). "JunD-deficiency-derived ROS elevation enhances HIF-1α accumulation and stimulates the CXCL12/CXCR4 pathway, which activates RhoA-GTPase to promote myofibroblast differentiation in TME, facilitating tumor metastasis." (PMID 40847302, 2025). "Under hypoxic tumor microenvironment, HIF-1α is more likely to regulate the expression of glycolysis and cell survival genes." (PMID 40246814, 2025). "Decreased angiogenesis by either PAK1KO or PAK4KO further increased hypoxia in tumours, showing increased HIF-1α staining in the PAK1KO or PAK4KO tumour tissues compared to the WT tumour tissues." (PMID 40943273, 2025). "IL-6 also promoted angiogenesis, tumor invasion, and metastasis through the regulation of hypoxia-inducible factor 1α (HIF-1α), matrix metalloproteinases (MMP2, MMP7, MMP9), and vascular endothelial growth factor (VEGF)." (PMID 40160826, 2025). "Total RNA was extracted, and transcript levels of HIF-1α, a key regulator of tumor survival under hostile microenvironmental conditions, were assessed by RT-qPCR." (PMID 41323785, 2025). "By enhancing glycolysis, HIF-1α facilitates the metabolic reprogramming necessary for tumor cell survival and growth in the oxygen-deprived tumor microenvironment." (PMID 40901111, 2025). "HT’s capacity to modulate tumor progression via interaction with HIF-1α was also reported in breast cancer cells." (PMID 40002421, 2025). "Both in vivo experiments demonstrated that the tumor growth was clearly suppressed by the combination of HIF-1α inhibition and KetoCal®." (PMID 41465202, 2025). "A higher frequency of HIF1α-positive tumor-infiltrating NK cells were observed in VHL mutant RCC tumor spheroids compared with VHL-restored RCC tumor spheroids." (PMID 40736709, 2025).